HMGB2 (high mobility group box 2)
Diseases named in the same sentence as HMGB2 in open-access papers (continued):
Sharing a sentence is not in itself a finding about the gene and the disease.
hepatocellular carcinoma (14 papers, 2013 to 2025). A malignant tumor that arises from hepatocytes. "Overexpression of high-mobility group box 2 was associated with tumor aggressiveness and prognosis of hepatocellular carcinoma." (PMID 28396617, 2017). "Overexpression of HMGB2 in hepatocellular carcinoma is associated with poor prognosis and tumor development." (PMID 24993133, 2014). "HMGB2 overexpression has been associated with resistance to cisplatin in head and neck squamous cell carcinoma, as well as tumor aggressiveness and prognosis of hepatocellular carcinoma." (PMID 36614297, 2023). "For instance, in hepatocellular carcinoma (HCC), intrinsic upregulation of high mobility group box 2 (HMGB2) is associated with T cell exhaustion within an extrinsically immunosuppressive microenvironment." (PMID 41050070, 2025). "Future research should aim to increase the sample size to validate these results and further investigate the functional roles of TOP2A and HMGB2 in the pathogenesis and treatment resistance of hepatocellular carcinoma (HB)." (PMID 40099956, 2025). "In hepatocellular carcinoma, ac4C modification of HMGB2 mRNA promotes eEF2 binding and translation elongation, driving tumor growth and metastasis." (PMID 40588654, 2025). "Then, overexpression of HMGB2 has been found in different kinds of human cancers, such as skin cancer, glioblastoma, hepatocellular carcinoma and pancreatic cancer." (PMID 33407071, 2021). "Overexpression of HMGB2 has been recognized in several types of tumors, including skin cancer, hepatocellular carcinoma, bladder carcinoma and had been correlated with tumor progression and angiogenesis." (PMID 26011628, 2015). "In addition, HMGB2 has been proved to be an independent influencing factor of the patient’s prognosis by its protein or mRNA level in hepatocellular carcinoma, epithelial ovarian cancer and glioblastoma multiforme." (PMID 35601497, 2022). "Moreover, in hepatocellular carcinoma (HCC), eEF2 enhances translation of HMGB2 mRNA, promoting tumor growth and metastasis." (PMID 39707196, 2024).
glioma (13 papers, 2015 to 2025). A benign or malignant brain and spinal cord tumor that arises from glial cells (astrocytes, oligodendrocytes, ependymal cells). "Although HMGB2 is the only member of the HMGB family with increased expression in gliomas compared to normal brain tissue and associated with survival in grades 2 and 3 gliomas, in GBMs, this association is controversial." (PMID 38672598, 2024). "We then sought to investigate the relationship between HMGB2 mRNA expression with glioma grade, possible underlying genomic and/or epigenomic regulatory mechanisms, and patient survival using public datasets." (PMID 38672598, 2024). "Here, we performed an extensive multi-omics study to discover and validate of HMGB2 as an early diagnostic and/or predictive marker of glioma progression and demonstrated one possible regulatory epigenetic mechanism of gene expression." (PMID 38672598, 2024). "Increased HMGB2 expression with grade in gliomas probably reflects the loss of cell differentiation and enhanced proliferative activity during glioma progression." (PMID 38672598, 2024). "In public databases, rare (0.39%) gene mutations were observed in HMGB2, and only 2% of the cases presented gene amplification (N = 1) or deep deletion (N = 14), all but one observed in the TCGA dataset labeled “lower grade gliomas”." (PMID 38672598, 2024). "To our knowledge, we have shown for the first time that DNA methylation of CpG islands located at the body of HMGB2 (cg19371349, cg21499459, cg08269316) also, at least in part, regulates HMGB2 expression and is strongly associated with OS in grades 2 and 3 gliomas." (PMID 38672598, 2024). "We identified HMGB2 as a potential biomarker of glioma evolution and predictive of response to treatment in more than 300 adult-type gliomas, using molecular profiling and immunohistochemistry, which are highly accessible for most pathology laboratories." (PMID 38672598, 2024). "Nonetheless, HMGB2 mRNA expression significantly increased with glioma grade (mRNASeq_325 dataset—ANOVA p = 3 × 10−25) in CGGA." (PMID 38672598, 2024). "Since we observed a good reliability of IHC staining in grades 2 and 3 gliomas, here we sought to thoroughly characterize HMGB2 expression in validation cohort 2, a large cohort of grade 4 astrocytomas originally diagnosed as GBMs and arranged in 12 TMAs." (PMID 38672598, 2024). "Upregulation of anti-apoptotic and cell proliferation pathways was observed in the HG areas in diffuse gliomas, and HMGB2 was identified as a potential driver of glioma progression." (PMID 38672598, 2024). "In grades 2 and 3 gliomas, IDH mutations seemed to be related to lower HMGB2 expression; however, in grade 4 astrocytomas, HMGB2 expression was significantly higher in A4IDHmut, which bear CDKN2A/B homozygous deletions, compared to GBMs at IHC." (PMID 38672598, 2024). "Among the positively correlated genes, evidence shows that GNG5, HMGB2, PCNA and HSPB11 can induce the proliferation and metastasis of glioma, causing poor prognosis and reducing the OS of patients with glioma." (PMID 34953037, 2022). "In cervical cancer, pancreatic cancer, glioma, and ovarian cancer, the HMGB2 was reported as a reliable prognosis predictor." (PMID 35962344, 2022). "In glioma cells, miR-130a negatively regulates the oncogenic functions of HMGB2, and miR139-5p regulates the progression of osteosarcoma by modulating HMGB2 expression." (PMID 35159393, 2022). "As a target gene of mi-R130a, HMGB2 controls the proliferation and epithelial mesenchymal transition of glioma cells." (PMID 34123852, 2021). "In another study, the lower expression of miR-130a-5p resulted in a reduced suppression of miR-130a-5p on HMGB2, thus contributing to glioma growth and metastasis." (PMID 33245102, 2020). "The results showed that the HMGB2 promoter had the highest activity in glioma cell lines among all promoters." (PMID 26074975, 2015).
glioma (continued). "Glioma-specific transgene expression cassette under combinatory control of HMGB2 promoter and 4 × miR-199a-3p targeting sequences (pHMGB2-mir199a3pT) was constructed." (PMID 26074975, 2015). "Based on literatures, the astroglial lineage-specific promoter GFAP, the tumor-specific promoter Survivin, and the glioma-specific promoter HMGB2 were chosen as candidates." (PMID 26074975, 2015). "Our approach of characterizing the proteomic profile of histopathology-targeted areas was successful in depicting temporo-spatial heterogeneity in diffuse astrocytomas and identified HMGB2 as a valuable, yet poorly explored, putative enabler of glioma progression." (PMID 38672598, 2024). "Therefore, there is a knowledge gap about the role of HMGB2 in glioma progression and treatment response." (PMID 38672598, 2024). "We sought to achieve the following: (i) identify proteins and molecular pathways involved in glioma evolution; and (ii) validate the high mobility group protein B2 (HMGB2) as a key player in tumor progression and as a prognostic/predictive biomarker for diffuse astrocytomas." (PMID 38672598, 2024). "In this study, five prognosis-related differentially expressed immune-related genes (PR-DE-IRGs) (CCNA2, HMGB2, CASP3, APOBEC3C, and BMP2) highly associated with glioma were identified for a prognostic model through weighted gene co-expression network analysis, univariate Cox and lasso regression." (PMID 35601497, 2022). "Additionally, five DDRGs (CDK4、HMGB2、WEE1、SMC3 and GADD45G) were selected to construct a DDRGs signature for glioma, stratifying patients into low- and high-risk groups." (PMID 34123852, 2021). "In the glioma cells, miR-130a-5p overexpression exercised repressive effects by targeting HMGB2." (PMID 33658008, 2021). "Those molecular GBMs had HMGB2 mRNA expression significantly higher than the other confirmed grades 2 and 3 astrocytomas and oligodendrogliomas, including “low-grade IDHwt astrocytomas” without other molecular alterations, which would now be classified as glioma, NEC." (PMID 38672598, 2024). "In our in-house cohort, the expression levels of CD274, HMGB2, RAC2, RIN3, and SOD3 were elevated in WHO grade IV gliomas compared to grades II/III." (PMID 40852729, 2025). "The IHC staining images of HMGB2, CCNA2, and CASP3 demonstrated their differences in protein expression between glioma and normal brain tissues, further supporting the stability of the model." (PMID 35601497, 2022). "We only observed higher expression of three genes (HMGB2, CCNA2 and CASP3) in the glioma tissues, consistent with the conclusions from the previous analysis based on the TCGA cohort." (PMID 35601497, 2022). "The forest map of Cox regression analysis indicated that SMC3 and GADD45G were positively correlated with the prognosis of patients with glioma, whereas CDK4, WEE1, and HMGB2 were negatively correlated with prognosis." (PMID 34123852, 2021). "Nevertheless, the association of HMGB2 expression with IDH status, and the relative expression in non-neoplastic tissue adjacent to an infiltrative glioma, remained elusive." (PMID 38672598, 2024). "The difference in HMGB2 expression between IDHwt and IDHmut gliomas was not consistent across our cohorts and public data." (PMID 38672598, 2024). "In terms of prognostic analysis, consistent with our previous results, high expression of CDK4, HMGB2, and WEE1 could lead to poor prognosis of glioma; however, gliomas with high expression of SMC3 and GADD45G were linked to longer survival." (PMID 34123852, 2021). "We have shown here a combinatorial transgene expression system DoFIT, which couples glioma-specific promoter HMGB2 and miR-199a-3p regulation to enable high level of transgene activation upon VSV-G-mediated NSC/glioma cell fusion but remains silenced in NSC vectors under off-target conditions." (PMID 26074975, 2015).
ovarian carcinoma (12 papers, 2016 to 2025). A malignant neoplasm originating from the surface ovarian epithelium. "As a result, they have shown upregulation of LINC00974 and HMGB2 mRNA expressions in ovarian cancer cells, while miR-33a expression (which directly targets HMGB2) was downregulated." (PMID 35907803, 2022). "So, silencing of LINC00974 by sponging miR-33a suppressed cell proliferation, invasion and EMT of cancer cells, suggesting the importance of LINC00974/miR-33a/HMGB2 axis in the progression of ovarian cancer." (PMID 35907803, 2022). "Recent researchers revealed that CENPU highly expressed in ovarian cancer samples and that overexpression of CENPU augments ovarian cancer aggressiveness by regulating high-mobility group box 2 (HMGB2)." (PMID 34957303, 2021). "HMGB1 and HMGB2 expression is augmented in a number of tumors, such as human gastric, breast, and ovarian cancer (and refs. therein)." (PMID 33076532, 2020). "We have determined the first interactome of HMGB1 and HMGB2 in epithelial ovarian cancer (the EOC-HMGB interactome)." (PMID 32867128, 2020). "To examine the relevance of the HMGB2-TOP1cc-cGAS pathway in immune checkpoint blockade treatment, we utilized an immune competent syngeneic ovarian cancer ID8-Defb29/Vegf-a mouse model." (PMID 32075966, 2020). "HMGB2 co-localized with γH2AX in the CCF in senescent OVCAR3 ovarian cancer cells induced by either cisplatin or etoposide." (PMID 32075966, 2020). "HMGB1 and HMGB2 genes were silenced in SKOV-3 and PEO1 EOC cell lines and levels of mRNA from 4 detected interacting partners of HMGB1 or HMGB2 in ovary cancer, COMMD1, MIEN1, NOP53 and ZNF428, were analyzed by qRT-PCR as explained in Materials and Methods." (PMID 32867128, 2020). "Considering that HMGB1 and HMGB2 proteins have been associated to drug resistance during cancer treatment we also reviewed available literature to see whether the proteins detected in our interactome study could also be related to this unfavorable event in ovary cancer treatment." (PMID 32867128, 2020). "HMGB1 and HMGB2 interact with each other and they have common interactors like the nuclear hormonal receptors which are deregulated in prostate and ovarian cancers." (PMID 26682011, 2016). "CENPU facilitates aggressiveness ability and progression of ovarian cancer via HMGB2." (PMID 34872447, 2021). "The proteins HMGB1, HMGB2, HSC70, GRP58, and GAPD form a nuclear complex, which alters DNA conformation, and they have been associated in vivo with resistance to chemotherapeutic drugs in ovarian cancer patients." (PMID 26682011, 2016). "In ovarian cancer cell lines SKOV3 and OVCAR3, HMGB2 knockdown also led to a marked reduction in proliferation." (PMID 40396172, 2025). "In ovarian cancer cell lines (SKOV3 and OVCAR3), HMGB2 knockdown significantly suppressed migration." (PMID 40396172, 2025). "In ovarian cancer models, SKOV3 and OVCAR3 cells, HMGB2 knockdown followed by Palbociclib treatment resulted in significant inhibition of cell proliferation." (PMID 40396172, 2025). "HMGB2 is identified as a downstream factor of CENPU, and CENPU enhances the expression level of HMGB2 in ovarian cancer cells." (PMID 34872447, 2021). "HMGB2 is found to be downstream of CENPU, and CENPU promoted malignancy and development of ovarian cancer via HMGB2." (PMID 34872447, 2021). "We have experimentally probed that HMGB1, HMGB2 and two of their partners, MIEN1 and NOP53 are also involved in the response of ovarian cancer cells to several drugs used in chemotherapy against EOC." (PMID 32867128, 2020). "With these precedents we decided to investigate the role of HMGB1, HMGB2, MIEN1 and NOP53 in cell viability as well as in response and sensitivity to drugs currently used in ovarian cancer therapy." (PMID 32867128, 2020). "Expression changes of HMGB1, HMGB2, MIEN1 and NOP53 genes have been evaluated in response to drugs usually employed in ovarian cancer treatments: bevacizumab, olaparib, paclitaxel or carboplatin." (PMID 32867128, 2020).
ovarian carcinoma (continued). "We tested the effect of four compounds, used in ovary-cancer therapy in the expression of the genes HMGB1, HMGB2, MIEN1 and NOP53 in cultured cancerous SKOV-3 cells and in non-cancerous IOSE-80 ovarian cells." (PMID 32867128, 2020). "In ovarian cancer cell lines (SKOV3 and OVCAR3), HMGB2 knockdown markedly reduced cell invasion." (PMID 40396172, 2025). "Interestingly, we have shown in our study that HMGB1, HMGB2 and their EOC-HMGB-interactome partners MIEN1 and NOP53 are involved in the response to carboplatin, or drugs nowadays used in ovarian cancer treatment, such as bevacizumab, olaparib and paclitaxel." (PMID 32867128, 2020). "Indeed, no data are available about the role of HMGB1 or HMGB2 in the resistance to olaparib or bevacizumab in the treatment of ovarian cancer." (PMID 32867128, 2020).
melanoma (10 papers, 2021 to 2025). A malignant, usually aggressive tumor composed of atypical, neoplastic melanocytes. "Similarly, the in vitro confinement of A375 human melanoma cells caused nuclear HMGB2 intensity to approximately double relative to unconfined cells (P = 1.42 × 10−7)." (PMID 40866703, 2025). "To directly test the role of HMGB2 in melanoma invasion, we used in vitro invasion assays and found that targeting HMGB2 with siRNA significantly impaired invasion (P = 0.0133), whereas overexpression of HMGB2 increased invasion (P = 0.0180)." (PMID 40866703, 2025). "Together, our results support a role for confinement-mediated upregulation of HMGB2 inducing a pro-invasive and drug-tolerant state in melanoma." (PMID 40866703, 2025). "Mechanical confinement of cancer cells at the tumour–microenvironment interface induces phenotype switching through chromatin remodelling by HMGB2, leading to a more invasive and drug-resistant state in melanoma." (PMID 40866703, 2025). "To validate our transcriptomic results indicating that HMGB2 is upregulated at the invasive front, we examined HMGB2 expression in zebrafish melanoma tissue sections." (PMID 40866703, 2025). "We examined a human melanoma tissue microarray to look for evidence of interface cells with elongated nuclei, high HMGB2 concentrations and perinuclear acetylated tubulin." (PMID 40866703, 2025). "HMGB2 overexpression significantly impaired melanoma response to dabrafenib/trametinib in vivo (P = 0.043)." (PMID 40866703, 2025). "According to a recent study, HMGB2− CD8+ T cells promoted malignancy, although HMGB2 maintained the exhausted status of CD8+ T cells in melanoma and chronic viral infections." (PMID 40315321, 2025). "We also observed decreased Hmgb2−/− Tpex cells in melanoma tumors and tumor-draining lymph nodes, indicating HMGB2 sustains exhausted T cells in multiple models of persistent antigen." (PMID 37704621, 2023). "We observed significantly decreased frequencies of Hmgb2−/− P14 T cells compared to WT in the tumor and tumor-draining lymph nodes (TdLNs) at day 18 post melanoma cell injection." (PMID 37704621, 2023). "HMGB2 down-regulates the NF-κB axis to reduce inflammatory damage, and miR-329 inhibits melanoma progression by down-regulating HMGB2 via the β-catenin pathway." (PMID 36568211, 2022). "Increasing evidence suggests that HMGB2 is involved in various malignancies like prostate cancer, cervical cancer, lung cancer, melanoma, pancreatic ductal adenocarcinoma (PDAC), and GC." (PMID 36568211, 2022). "Among down-regulated genes, the analysis showed several experimentally validated target genes, such as E2F7, MAP2K1 (also known as MEK1), CCNG1, HMGB2, SIRT1, belonging to key signaling pathways frequently associated to melanoma." (PMID 33670365, 2021). "We investigated the functional domains that control HMGB2 localization and activity in melanoma." (PMID 40866703, 2025). "We then investigated whether the upregulation of HMGB2 and acetylated tubulin by confined cells is melanoma-specific or exhibited across other cancer types." (PMID 40866703, 2025). "In melanoma cells, silencing of the HMGB2 gene can weaken cell viability, and there is a targeted relationship between miR-329 and the HMGB2 gene, which can negatively regulate the HMGB2 gene and inhibit β- catenin pathway, thereby regulating cellular life activities." (PMID 38787178, 2024). "In an experimental study, HMGB2 was observed to be highly expressed in melanoma, whose silence impeded cell proliferation and invasion, yet promoted cell cycle arrest and apoptosis, leading to melanoma regression, indicating that HMGB2 contributed to melanoma promotion." (PMID 34777483, 2021). "Interestingly, HMGB2 and β-catenin have been reported to cooperate to promote melanoma progression." (PMID 34725363, 2021).
melanoma (continued). "Together, our results demonstrate that confined melanoma cells remodel cytoskeletal and nuclear structures to reinforce the cell against mechanical force, resulting in LINC complex-mediated HMGB2 upregulation and nuclear stiffening." (PMID 40866703, 2025). "To test the role of HMGB2 in phenotype switching in vivo, we generated BRAFV600E melanomas in zebrafish, in which zebrafish hmgb2a and hmgb2b were inactivated by CRISPR." (PMID 40866703, 2025). "HMGB proteins (specifically HMGB1) are involved in the response to immunogenic cell death occurring after RT, and HMGB2 is a known regulator of CD8+ T cells, required for anti-melanoma response." (PMID 38672598, 2024). "Although we cannot rule out a role for HMGB2–RNA binding in melanoma on the basis of our current data, characterizing this interaction will be an important area for future study." (PMID 40866703, 2025).